IL7R (interleukin 7 receptor)
Diseases named in the same sentence as IL7R in open-access papers (continued):
Sharing a sentence is not in itself a finding about the gene and the disease.
inflammatory bowel disease (13 papers, 2012 to 2025). A spectrum of small and large bowel inflammatory diseases of unknown etiology. "Overexpression of IL-7Rα is linked to increased severity of inflammatory bowel disease." (PMID 24430176, 2014). "Individuals with inflammatory bowel disease have high levels of IL-7 and IL-7R and high activity of the colon-specific mucosal IL-7R signaling pathway." (PMID 40240976, 2025). "We used pharmacological blockade of IL-7R to understand the mechanisms involved in IL-7R-mediated inflammatory bowel disease by analyzing immune cell profiles, circulating and colon proteins, and colon gene expression." (PMID 23057802, 2012). "Studies of tissues from patients with Inflammatory Bowel Disease (IBD) found that an EOMES+ IL7R- CCR5+ Tr1 population is diminished in the inflamed intestinal lamina propria of patients with IBD, relative to matched healthy control tissue." (PMID 37654482, 2023).
systemic lupus erythematosus (12 papers, 2009 to 2025). An autoimmune multi-organ disease typically associated with vasculopathy and autoantibody production. "Of note, recent observations also highlight the potential involvement of IL-7/IL-7R in other autoimmune disorders, such as systemic lupus erythematosus and Sjögren’s syndrome." (PMID 27729062, 2016). "To confirm these observations also in an in vivo setting, we characterized the IL-2R and IL-7R profiles of T cells from systemic lupus erythematosus (SLE) patients undergoing IL-2 immunotherapy." (PMID 41310351, 2025).
atherosclerosis (11 papers, 2011 to 2024). A disease characterized by the build-up of fatty material and calcium deposition in the arterial wall resulting in partial or complete occlusion of the arterial lumen. "IL-7r may contribute to chemokine recruitment in atherosclerosis-associated ATLO development." (PMID 34206780, 2021). "The immune-associated genes in both atherosclerosis and osteoporosis from WGCNA mainly included TREM1, CYBB, CCR1, CD83, CD52, IL7R, and THBS1." (PMID 35937806, 2022). "IL-7 is also hypothesized to be a key regulator in atherosclerosis through its receptor (IL-7r) and through artery tertiary lymphoid organs (ATLOs)." (PMID 34206780, 2021). "Furthermore, anti-inflammatory/inflammation-regulatory genes (like IL7R, ANXA1, and KLRB1) and pathways (like regulation of IL-2 production) were decreased in CD4+ T cells (T_1, T_2, and T_3) from atherosclerosis compared with those from NC." (PMID 37706320, 2023). "Furthermore, other upregulated genes were those of the pro-inflammatory interleukins IL3RA, IL7R, IL8, IL11, usually secreted by immune system cells, and of the NF-κB family (NF-κBIA, NF-κBIZ, NF-κBIE), nuclear transcription factors known to be involved in the development of atherosclerosis." (PMID 28224128, 2017).
malaria (11 papers, 2008 to 2026). Malaria is a serious and sometimes fatal disease caused by a parasite that commonly infects a certain type of mosquito which feeds on humans. "Our study is the first large-scale attempt to determine the genetic basis of placental infection in malaria, and suggests an important unexpected role of the IL-7/IL-7R pathway for the susceptibility of this important clinical condition." (PMID 21949827, 2011). "In summary, we have identified a population of induced Foxp3− regulatory (Tr1) T cells, characterised by production of IL-10 and down regulation of IL-7Rα, that modulates the inflammatory response to malaria." (PMID 18401464, 2008). "In a mouse model of malaria using P. berghei, the parasite ortholog of macrophage migration inhibitory factor (PMIF) induced the upregulation of T-bet and IFN-γ and the downregulation of IL-7R, IL-7, IL-2 and Bcl-2 in T cells specific for the parasite." (PMID 25559491, 2015).
liver fibrosis (10 papers, 2014 to 2026). "MR analysis confirmed a significant positive causal effect of IL7R on liver fibrosis." (PMID 41948344, 2026). "The research has confirmed that reduced miR-122-5p is closely related with the progression of HBV-induced liver fibrosis, and miR-122-5p can effectively impeded the deterioration of the symptom via targeting IL7R." (PMID 36193503, 2022).
lung adenocarcinoma (9 papers, 2015 to 2024). A carcinoma that arises from the lung and is characterized by the presence of malignant glandular epithelial cells. "Moreover, overexpression of IL-7R in lung adenocarcinomas was associated with tumor budding, which in turn has been associated with unfavorable outcome." (PMID 27866242, 2017). "Conversely, IL7R has been indicated as a favorable prognostic maker and a potential target for immunotherapy in human lung adenocarcinoma." (PMID 39911484, 2024). "The results of Western blotting showed that BTG2, TLR2, and IL7R proteins were markedly downregulated in lung adenocarcinoma cell line A549, while CCL20 protein was markedly upregulated." (PMID 35372503, 2022). "Then, we analyzed the relationship between IL7R and clinical features, and the survival of patients with lung adenocarcinoma was analyzed using datasets from TCGA." (PMID 35264973, 2022). "Survival analysis showed the overall survival of patients with lung adenocarcinoma was positively correlated with the expression of B cells, DC cells, and IL7R." (PMID 35264973, 2022). "Above all, we believe IL7R inhibits the progression of lung adenocarcinoma by modulating the infiltration levels of B cells, DC cells, and CD4 + T cells, thus affecting the survival of patients." (PMID 35264973, 2022). "In lung adenocarcinoma tissue samples, the expression of IL7R is mainly located in the cytoplasm of tumor cells, and most of them are negative or weakly positive." (PMID 35264973, 2022). "IL7R expression was positively correlated with the overall survival and progression-free survival of lung adenocarcinoma patients and negatively correlated with tumor size." (PMID 35264973, 2022). "We also found that the expression of IL7R in normal lung epithelial cell line was higher than that in lung adenocarcinoma cell lines." (PMID 35264973, 2022). "Il7r is a key player in the maturation of B and T cells, and it was demonstrated that its expression is positively correlated with immune cell infiltration in the tumor microenvironment of lung adenocarcinoma." (PMID 37932771, 2023). "In conclusion, IL7R is a biomarker for predicting a good prognosis of lung adenocarcinoma." (PMID 35264973, 2022). "IL7R could be a beneficial prognostic marker in patients with lung adenocarcinoma and has great potential in immune therapy." (PMID 35264973, 2022). "In addition, we analyzed the expression of IL7R in lung adenocarcinoma tissue samples with different growth patterns." (PMID 35264973, 2022). "Survival analysis showed IL7R was an independent prognostic factor of lung adenocarcinoma." (PMID 35264973, 2022). "IL7R could also be a potential therapeutic target for the treatment of lung adenocarcinoma." (PMID 35264973, 2022). "Next, the TIL ratio of TCGA lung adenocarcinoma samples was estimated by Timer algorithm, and the relationship between the changes of TIL components and the expression of IL7R was analyzed." (PMID 35264973, 2022). "Using tissue microarray and immunohistochemistry, Suzuki and colleagues found that tumor interleukin-12 receptor β2 (IL-12Rβ2), IL-7R, and stromal FoxP3/CD3 ratio are independent predictors of recurrence in patients with stage I lung adenocarcinoma." (PMID 25950176, 2015). "To explore the mechanism of IL7R affecting the TME of lung adenocarcinoma, we analyzed the relationship between IL7R expression and the components of tumor-infiltrating lymphocytes in the TME of lung adenocarcinoma." (PMID 35264973, 2022). "Further verification was conducted in 40 tissue samples from LUAD patients and 35 cases of adjacent normal tissues, and it was found that the expression of IL7R was negative in lung adenocarcinoma tissues and positive in adjacent normal lung tissues." (PMID 35264973, 2022). "Therefore, we speculate that IL7R may be involved in the regulation of lymphocyte infiltration in the TME, thus influencing the progression of lung adenocarcinoma." (PMID 35264973, 2022).
primary immunodeficiency (9 papers, 2012 to 2025). "For the primary immunodeficiency subclone, downregulation of IL7R mRNA was associated with poor survival." (PMID 32978398, 2020). "Our results revealed significant associations between specific metabolites and genes, indicating that low-concentration exposure to BHPF affects endometrial epithelial cells by targeting pathways related to primary immunodeficiency, in which the key genes are IL7R and PTPRC." (PMID 39997915, 2025). "Notably, CD79A and IL7R were involved in the primary immunodeficiency pathway (FDR = 1.43 × 10−3), which represents essential disruptions in adaptive immune cell development and function." (PMID 40725191, 2025). "The same applies for targeted gene panels that include IL7R; at Great Ormond Street Hospital, we now use ExomeDepth for CNV detection in samples analyzed with the targeted primary immunodeficiency gene panel." (PMID 27807805, 2017). "IL7R (Interleukin 7 receptor) participated in the Jak-STAT signaling pathway, hematopoietic cell lineage, primary immunodeficiency, and cytokine-cytokine receptor interactions in the KEGG pathway database for cold-pattern RA patients." (PMID 22536280, 2012). "Enrichment Kyoto Encyclopedia of Genes and Genomes (KEGG) analysis revealed DEGs engaged into three metabolic pathways: NF-kappa B signaling pathway (ZAP70, LCK, LTB), T cell receptor signaling pathway (ITK, ZAP70, LCK), and primary immunodeficiency (ZAP70, IL7R, LCK)." (PMID 30917529, 2019).
sarcoidosis (9 papers, 2012 to 2024). Sarcoidosis is a multisystemic disorder of unknown cause characterized by the formation of immune granulomas in involved organs. "Polymorphisms in the CD127 (IL-7R) gene are known risk factors for sarcoidosis development, and the IL-7 receptor is crucial during T cell activation, homeostasis, and differentiation." (PMID 28955342, 2017). "Of the 31 TCR/JS/CCR-gene signature genes, 8/31 genes were cited in the sarcoidosis literature with CD28, IFNG, IL7R, AKT3, IL2RA, IL2RB, and STAT4 demonstrating a robust relationship with these terms." (PMID 22984568, 2012). "Sarcoidosis unique upregulated DEGs in response to LPS were FOXP1 (Forkhead Box P1), DDIT4 (DNA Damage Inducible Transcript 4), and IL7R, and unique downregulated DEGs in sarcoidosis were PYCARD (Caspase Recruitment Domain-Containing Protein 5), CD4, and PLD3 (Phospholipase D Family Member 3)." (PMID 39284999, 2024).
experimental autoimmune encephalomyelitis (7 papers, 2017 to 2025). An autoimmune demyelinating disease of the central nervous system that is produced experimentally in animals by the injection of homogenized brain or spinal cord in Freund's adjuvant. "IL-7R-deficient mice showed resistance to the induction of experimental autoimmune encephalomyelitis and T cell response." (PMID 40323267, 2025). "Ligation of IL7R by IL-7 was found to be required for autoimmune neuroinflammation in experimental autoimmune encephalomyelitis." (PMID 31023360, 2019). "Although IL7R was not properly matched it was demonstrated that IL7R was enriched on Th17 cells and could serve as marker of Th17 cells in experimental autoimmune encephalomyelitis (a common animal model of MS)." (PMID 29435179, 2018).
hepatocellular carcinoma (7 papers, 2015 to 2025). A malignant tumor that arises from hepatocytes. "Our data demonstrate that HBX can upregulate IL-7R via NF-κB and Notch1 pathways to facilitate the activation of intracellular pathways and expression of associated molecules, and contribute to proliferation and migration of hepatoma cells." (PMID 27821177, 2016). "Additionally, these results imply that autocrine and paracrine IL-7 may activate intracellular signaling pathways and associated molecules in hepatoma cells via interacting with increased IL-7R mediated by HBX." (PMID 27821177, 2016). "The role of NF-κB and Notch1 pathways in HBX-mediated expression of IL-7R in hepatoma cells was examined." (PMID 27821177, 2016). "Gene and protein expression levels of IL-7R were examined in hepatoma cells transfected with hepatitis B virus (HBV) plasmids and in hepatoma cells transfected with the multifunctional nonstructural protein X (HBX)." (PMID 27821177, 2016). "When HBX-positive cells were treated with IL-7R shRNA, the migration of hepatoma cells mediated by HBX was inhibited." (PMID 27821177, 2016). "Using microarray gene expression analysis, we have shown that the expression of IL-7R was upregulated in HBV-transfected hepatoma cells." (PMID 27821177, 2016). "As expected, we found increased expression levels of IL-7R in stable HBX-transfected hepatoma cells when compared with those in control cells." (PMID 27821177, 2016). "Taken together, our results suggest that increased IL-7R is involved in HBX-mediated proliferation and migration of hepatoma cells, and that activation of IL-7R mainly depends on its interaction with IL-7." (PMID 27821177, 2016). "The expression of IL-7R was increased in hepatoma cells transfected with HBV plasmids; HBX was responsible for the HBV-mediated upregulation of IL-7R." (PMID 27821177, 2016). "The results showed that compared with HBV-transfected hepatoma cells, the expression of IL-7R gene and protein were decreased in hepatoma cells transfected with the HBV mutant." (PMID 27821177, 2016). "This suggests that in the hepatoma microenvironment, IL-7, secreted by the tumor, as well as by other types of cells, contributes to the abnormal activation of IL-7R in hepatoma cells." (PMID 27821177, 2016). "Meanwhile, IL7R has been described as a suppressor gene in hepatocellular carcinoma." (PMID 36672342, 2023). "We investigated whether increased proliferation and migration of hepatoma cells mediated by HBX was dependent on IL-7R." (PMID 27821177, 2016). "Additionally, the results of RT-PCR and western blotting analysis further confirmed the results of the microarray, which indicated that HBV was able to enhance the expression of IL-7R in hepatoma cells." (PMID 27821177, 2016). "In this study, we found that HBV could increase the expression of IL-7R through HBX in hepatoma cells." (PMID 27821177, 2016). "Because the role of IL-7 in EMT is mainly dependent on its interaction with IL-7R, and current studies indicate that HBX uses various mechanisms to induce EMT in hepatoma cells, we examined whether IL-7R facilitates EMT in HBX-mediated HCC." (PMID 27821177, 2016). "Based on these reports, we speculated that HBX may activate NF-κB and/or Notch 1 pathway to drive IL-7R expression in hepatoma cells." (PMID 27821177, 2016). "In conclusion, we found that HBV could upregulate the expression of IL-7R via HBX to increase the activation of intracellular pathways and expression of associated molecules, and contribute to the proliferation and migration of hepatoma cells." (PMID 27821177, 2016). "Consequently, we wished to examine whether HBX-mediated IL-7R was involved in the proliferation and migration of hepatoma cells." (PMID 27821177, 2016). "Therefore, one should not rule out the possible influence of IL7R polymorphisms in the development of end-stage of liver disease and hepatocellular carcinoma in HIV/HCV coinfected patients." (PMID 26123260, 2015).
hepatocellular carcinoma (continued). "For patients with hepatocellular carcinoma, the coexpression of CD161 and IL-7R enhances IL-2, TNF-α, and perforin expression which improve prognosis." (PMID 35028320, 2022). "Interleukin-7 receptor (IL-7R) is involved in the abnormal function of solid tumors, but the role and regulatory mechanisms of IL-7R in HBV-related hepatocellular carcinoma (HCC) are still unclear." (PMID 27821177, 2016). "When cells were treated with IL-7R shRNA, HBX-mediated proliferation in hepatoma cells was decreased." (PMID 27821177, 2016). "Furthermore, increased levels of IL-7R contributed to the HBX-induced proliferation and migration of hepatoma cells." (PMID 27821177, 2016). "Additionally, the role of IL-7R in HBX-mediated proliferation and migration of hepatoma cells was investigated." (PMID 27821177, 2016). "After treatment with IL-7R shRNA, the proliferation and migration of hepatoma cells, with or without exogenous IL-7 stimulation, were significantly decreased." (PMID 27821177, 2016). "Additionally, IL-7R was responsible for HBX-induced proliferation and migration ability of hepatoma cells." (PMID 27821177, 2016). "The activation of NF-κB pathways and expression of Notch1 were increased in hepatoma cells transfected with HBX, and inhibition of NF-κB and Notch1 pathways significantly decreased HBX-mediated expression of IL-7R." (PMID 27821177, 2016). "Although our results have shown that HBX can promote EMT in hepatoma cells, knockdown of IL-7R with IL-7R shRNA did not inhibit, but instead enhanced EMT, in hepatoma cells." (PMID 27821177, 2016). "When cells were treated with IL-7R shRNA, the expression of vimentin and β-catenin increased, while E-cadherin decreased significantly, suggesting that IL-7R had a negative role on EMT in hepatoma cells, and that HBX-mediated EMT in hepatoma cells was independent of IL-7R." (PMID 27821177, 2016).
non-small cell lung carcinoma (7 papers, 2010 to 2024). A group of at least three distinct histological types of lung cancer, including non-small cell squamous cell carcinoma, adenocarcinoma, and large cell carcinoma. "The high expression of IL-7 and IL-7R is highly positie correlated with clinic stage, lymph node metastasis, VEGF-D, LVD and poor prognosis in Non-small cell lung cancer." (PMID 21159243, 2010). "Moreover, IL-7/IL-7R-induced VEGF-D upregulation positively correlates with lymph node metastasis, clinical stages, and survival in human non-small cell lung cancer patients." (PMID 34575268, 2021).
Stroke (7 papers, 2020 to 2025). Sudden impairment of blood flow to a part of the brain due to occlusion or rupture of an artery to the brain. "The proportion of neutrophil distributed in the peripheral blood of stroke patients increased, in which the gene expression of IL7R, SLAMF1 and CCR7 were low, and vice versa." (PMID 32746852, 2020).
acute myeloid leukemia (6 papers, 2013 to 2024). Acute myeloid leukemia (AML) is a group of neoplasms arising from precursor cells committed to the myeloid cell-line differentiation. "We engineered T cells to constitutively secrete IL7 or to express an anti–acute myeloid leukemia–targeted IL7Rα–chimeric cytokine receptor (CCR) and characterized the phenotype of these cell types." (PMID 39186002, 2024). "In acute myeloid leukemia (AML), there is a significant enrichment of ILC1s in peripheral blood compared to healthy controls and a significant reduction in the production of IFN-γ, TNF, and IL-5/IL-13 in total ILCs defined as Lin-IL7R+." (PMID 38567059, 2023).
colon cancer (6 papers, 2016 to 2025). "This explains an associated with Il-7R expression and colon cancer development." (PMID 34573368, 2021). "IL-7R-α subunit expressions (mRNA and protein levels) were increased in colon cancer tissues compared to matching normal tissues." (PMID 34573368, 2021). "mRNA expressions and protein levels of TSLP, TSLPR-α subunit, and IL-7R-α subunit showed a 4-fold increase in colon cancer tissues when compared to normal colon tissues." (PMID 34573368, 2021). "TSLPR mRNA was detected in all three cell lines, which had higher expression levels than PBMCs from healthy donors we used as a positive control for TSLPR expression, while IL-7Rα mRNA expression levels were comparable in the colon cancer cell lines and PBMC." (PMID 26919238, 2016). "For C7 (CD8+ TEMRA/TEFF), there were 359 DEGs between colon cancer and rectal cancer, such as HSPA1L and IL7R were up-regulated, while CD8A and CTSW were down-regulated in colon cancer compared to that in rectal cancer." (PMID 33584715, 2020).